ZEB1 (zinc finger E-box binding homeobox 1)
Diseases named in the same sentence as ZEB1 in open-access papers (continued):
Sharing a sentence is not in itself a finding about the gene and the disease.
cancer (continued). "EMT can be induced in a number of ways, including by pleiotropically acting EMT-TFs including SNAI1/2 (Snail1/2), ZEB1/2 and TWIST1/215, these have been shown to have a role in cancer." (PMID 32269211, 2020). "ZEB1, a well-known regulator of EMT, has been proven to participate in the modulation of cell growth and metastasis in various types of cancers." (PMID 32850368, 2020). "Zeb1, Twist1, Snail, Slug, or treatment with TGF-β promote both tumorigenicity and stemness of cancer cells." (PMID 33297508, 2020). "It is not necessarily the epithelial or mesenchymal state that dictates cancer stem-like properties such as drug resistance; instead, they depend on the functions and mechanisms of action of EMT regulators, including ZEB1." (PMID 32266287, 2020). "This lncRNA acts as a ceRNA by sequestering miR-141-5p, which, in addition to increasing the levels of ZEB1, also upregulates TGF-β, favoring the EMT and cancer progression." (PMID 32987716, 2020). "It has been suggested that enhancing the expression of miR-203 is a potential strategy in sensitizing cancer cells to radiotherapy, since miR-203 binds to the 3′-UTR of ZEB1 to repress its expression." (PMID 32664703, 2020). "Zrt- and Irt-like protein 4 (ZIP4) can facilitate the growth of cancer cells and the EMT process via regulating cyclic AMP-responsive element-binding protein 1 (CREB1) and zinc finger E-box binding homeobox 1 (ZEB1), respectively." (PMID 32756339, 2020). "As induction of HIF-1α is known to deteriorate the state of cancer and EMT process is one of the hallmarks of metastasis in cancer, our findings uncover the role of neddylation between HIF-1α and ZEB1." (PMID 33097763, 2020). "Following neddylation blockade, we discovered that induction of ZEB1 was mediated by HIF-1α through the activation of the PI3K/Akt/mTOR pathway, emphasizing the role of neddylation in cancer migration." (PMID 33097763, 2020). "ZEB1 enhances IL-6 release and activates STAT3, which results in an increased proliferation potential of cancer cells." (PMID 32488850, 2020). "In this way, NOB downregulates NF-κB, Wnt, TGF-β, Snail, Slug, and ZEB1 as upstream mediators of EMT, resulting in the reduced metastasis of cancer cells." (PMID 32380783, 2020). "In this section, we provide an overview of ZEB1 and ZEB2 proteins to shed some light on their role in cancer cells." (PMID 32664703, 2020). "Therefore, the expression of ZEB1 may be a biomarker of poor clinical outcomes for cancer patients." (PMID 32014049, 2020). "ZEB1 regulates the EMT development, which accounts for the partial or whole transition of cancer cells with epithelial features to a mesenchymal status." (PMID 32667627, 2020). "In vitro overexpression of ZEB1 in therapy-naive cells results in downregulation of MITF, upregulation of cancer stem cell markers (e.g., NGFR and lysine demethylase 5B, JARID1B) and mesenchymal markers (e.g., VIM), and increased resistance to MAPKi." (PMID 32796736, 2020). "HIF-1α activates transcription factors, such as Snail, twist, and ZEB1, under hypoxic conditions, promoting EMT pathogenesis and leading to cancer cell acquisition of stem cell activity." (PMID 33062005, 2020). "Studies on cancer EMT revealed that transcriptional activation of ZEB1 by SLUG promoted EMT progression that decreased adhesion and increased migration of cancer cells." (PMID 32252322, 2020). "EMT-induced transcriptional repressor, Zinc finger e-box binding homeobox 1 (ZEB1) is recognized as a stimulator towards imparting an aggressive, metastatic, and therapy-resistant cancer phenotype." (PMID 33292221, 2020). "The accumulating data demonstrate that ZEB1 and ZEB2 proteins are able to enhance the invasion and migration of cancer cells." (PMID 32503307, 2020). "The transcription factors, SNAI1, SLUG, ZEB1, and ZEB2, that are involved in EMT, repress E-cadherin to promote the mesenchymal features of cancer cells." (PMID 32218208, 2020).
cancer (continued). "Accumulating data demonstrates that SNHG6 can induce EMT in cancer cells via targeting EMT-TFs such as TGF-β and ZEB1, making it an efficient target in suppressing metastasis of cancer cells." (PMID 32784711, 2020). "SNAI1 and ZEB1 are important transcription factors that promote the progress of EMT, and play a key role in the occurrence and development of a variety of cancers." (PMID 33148251, 2020). "ZEB1 is an EMT inducer that downregulates E-cadherin and induces the epithelial to mesenchymal transition in breast and other carcinomas." (PMID 32961774, 2020). "However, the potential role of ZEB1 (if any) in the cytoplasm of cancer cells remains unknown." (PMID 30910999, 2019). "At the molecular level, we showed that ATF4 significantly upregulates the mRNA and protein levels of ZEB1, which is a critical transcriptional repressor of E-cadherin and promotes EMT and cancer metastasis." (PMID 31064130, 2019). "Soluble factors, such as FGF2, secreted autonomously by cancer cells undergoing EMT, activate FGFR(IIIc) and ERK pathways to sustain high ZEB1/2 levels." (PMID 31682640, 2019). "Intense ZEB1 staining was observed in the hypoxic regions where CAIX was expressed abundantly, and ZEB1 was mainly distributed within cancer cell islets." (PMID 31263103, 2019). "Both EMT and cancer metastasis are stimulated by an increase in SNAI1, N-cadherin, Zeb1, and vimentin, and a decrease in E-cadherin." (PMID 30736337, 2019). "qPCR analyses revealed that the mesenchymal markers (i.e. SNAI1, SNAI2, ZEB1, ZEB2, CDH2, vimentin and fibronectin) expression was decreased in cancer EVs-exposed BRCA1-KO fibroblasts, while the expression of CDH1 was increased." (PMID 31200749, 2019). "Zeb1 is a well-known and powerful EMT-TF that promotes EMT, metastasis, and the generation of cancer stem cells in many types of malignancies, including CRC." (PMID 30979372, 2019). "We have identified several microRNAs (miRNAs) to elucidate the molecular link how AXT inhibits cancer cell metastasis by repressing MMP2 and ZEB1 expression." (PMID 31263239, 2019). "As a key driver of EMT, TGF-β plays an important role in tumorigenesis and cancer metastasis, and induces EMT by activating transcription factors of the Snail, Slug, Twist and ZEB1 families." (PMID 31402791, 2019). "As cancer advances in a MeS context, CTBP1 expression and/or activity would increase, leading to the repression of miR-205-5p and the upregulation of ZEB1, kick-starting the EMT process." (PMID 30931931, 2019). "We also observed a decrease in cancer invasion and migration from TQ treatment as well as a reduction in the expression of EMT-related genes, such as N-cadherin, TWIST, SLUG, SNAIL, ZEB1 and ZEB2, including downstream MUC4." (PMID 31141941, 2019). "It has been shown that Brg1 is capable of acting as a co-factor for Zeb1 to promote EMT and metastasis in a number of different cancer cells." (PMID 31750301, 2019). "ZEB1, ZEB2, SNAI1, and SNAI2 were significantly and positively correlated with the ESTIMATE immune score in all five cancer types examined." (PMID 31780722, 2019). "Other studies show that HIF1α activates EMT regulators including SIP1, ZEB1 SLUG, SNAIL or TWIST to promote of cancer cell metastasis." (PMID 31371307, 2019). "ZEB1 and ZEB2 are key modulators of cancer-initiating cell properties in HNSCC, EMT process, metastasis and cisplatin resistance." (PMID 30755200, 2019). "ZEB1 and ZEB2 are known to be extensively upregulated by TGF-β in both normal epithelial cells and cancer cells." (PMID 31682640, 2019). "It has been reported that the zinc finger E-box binding homeobox 1 (ZEB1) transcription factor is a key driver of EMT and is involved in resistance to cancer therapy." (PMID 31506427, 2019). "Zinc finger E-box binding homeobox 1 (ZEB1) is a transcriptional factor (TF) demonstrated as an oncogene regulating invasion, migration, EMT, and proliferation of diverse types of cancer cells." (PMID 31570691, 2019).
cancer (continued). "ZEB1, ZEB2, SNAI1, SNAI2 and FOXC2 exhibited consistent positive correlations with the ESTIMATE stromal score in all five cancer types." (PMID 31780722, 2019). "Zinc finger E-box binding homeobox 1 (ZEB1) is the key factor of Epithelial-mesenchymal transition (EMT) and cancer cells undergoing EMT show more chemoresistance." (PMID 30992025, 2019). "miR-34a inhibits cancer stemness via targeting CD44; miR-34a expression inhibits TGF-β-induced EMT and downregulates Snail, Slug and ZEB1 as well as the stemness factors (BMI1, CD44, CD133, OLFM4 and c-MYC)." (PMID 30885232, 2019). "Reciprocal repression between the Zeb1 and miR-200 family promotes EMT and thus cancer migration and invasion, a regulatory mechanism that is also reported for miR-1199–Zeb1 interactions." (PMID 29843425, 2018). "ZEB1, a member of the ZEB family of transcription factors, has been reported to be overexpressed in several human cancers, including HCC38–40." (PMID 29523781, 2018). "Recent studies further demonstrate that ZEB1 acts as a driver of epithelial to mesenchymal transition (EMT) and cancer progression, due to its pivotal role in the downregulation of epithelial genes, such as E-cadherin and the miR-200 family of microRNAs23–26." (PMID 29352223, 2018). "Various transcription factors such as Twist, Snail, Slug, ZEB1 and ZEB2 are known to orchestrate EMT by activating the crosstalk of signaling networks that confer traits of self-renewal and invasiveness to cancer cells." (PMID 29515112, 2018). "Of note, either knockdown Zeb1 or inhibit the phosphorylation of Akt activity, HMGB1 induced the migratory capacity of cancer cells was abrogated." (PMID 29615080, 2018). "Further analysis revealed that invasively growing cancer cells in Rf-HSEs express markers of EMT transition, like SNAIL2, N-cadherin and ZEB1." (PMID 29551776, 2018). "TGF-β would be the most responsible factor for induction of EMT by inducing EMT-inducing transcription factors in cancer cells, notably SNAIL, SLUG, ZEB1, TWIST, GOOSECOID, and FOXC2." (PMID 30453543, 2018). "Several of the predicted targets are known to be involved in cancer progression (E2F1, E2F5, ERBB, PTEN), invasion and metastasis (ZEB1/2, LRP-1)." (PMID 30510566, 2018). "These lncRNAs perform the important function role in cancer by regulating their neighboring protein-coding genes, which resembles lncRNA-HIT and protein-coding gene ZEB1." (PMID 29581707, 2018). "Consistent with our results that ZEB1 overexpression attenuates EPI- and ETOP-induced cell growth inhibition, ZEB1 has been shown to facilitate cancer cell proliferation in the presence of DNA damage." (PMID 29352223, 2018). "We checked six transcription factors (SLUG, SNAIL, TWIST 1/2, ZEB1/2), all of which are known to control the expression of E-CADHERIN in cancer cells." (PMID 29339729, 2018). "Here, we focus on ZEB1—a key driver of EMT—which can confertumor-initiating (stemness) and chemoresistance properties to cancer cells, and its expressioncorrelates with poor prognosis." (PMID 31069317, 2018). "As expected, we noted an upregulation of cancer stem cell markers LGR5 and CD44, as well as epithelial-to-mesenchymal transition marker ZEB1, in the spheroids." (PMID 29463813, 2018). "Once HIF-1α is increased, it can promote cancer cell EMT by inducing expressions of downstream genes like Twist-1 and ZEB1." (PMID 29435158, 2018). "Given the significant control that ZEB1 has in repressing E-Cadherin, it therefore serves as a driver of EMT and cancer progression." (PMID 32309604, 2018). "ZEB1 expression negatively correlates with E-cadherin expression and is associated with advanced diseases or metastasis, which indicates the relevance of ZEB1 induction of EMT and cancer development." (PMID 29510731, 2018).
cancer (continued). "This function of ZEB1 in promoting DDR is especially important for the survival and proliferation of cancer cells in the face of chemotherapeutic agents that induce massive DNA damage, which leads to chemoresistance." (PMID 29352223, 2018). "Conversely, increased N-cadherin, vimentin, fibronectin, Zeb1, Twist, and Snail expression and down-regulation of E-cadherin were detected in CLCA4 silenced cancer cells." (PMID 29190973, 2017). "Zinc finger E‐box binding protein 1 (ZEB1) and ZEB2 induce epithelial‐mesenchymal transition (EMT) and enhance cancer progression." (PMID 28618162, 2017). "The mammalian homologs of Zfh1 known as ZEB1 and ZEB2 have been largely studied for their role in cancer progression." (PMID 29072161, 2017). "The transcription factors of EMT, such as ZEB1, ZEB2, Snail1 and Snail2, control EMT phenotype, which triggers cancer cell invasion." (PMID 28145431, 2017). "A series of transcription factors have been reported to promote EMT process in cancer metastasis, including SNAL1, TWIST1, ZEB1, and SIP1 (ZEB2)." (PMID 28423728, 2017). "We screened for cancer cells expressing at least one EMT marker, such as ACTA2, EPCAM, CD44, THY1, VIM, FN1, ZEB1 or CDH1." (PMID 29079795, 2017). "This is also accompanied by increased expression of CXCL12, CXCL10, as well as markers of cancer progression, including CD44, ZEB1 and vimentin." (PMID 28445977, 2017). "During the EMT process, several EMT markers or inducers, including ZEB1 and SNAIL, are activated to promote the “stemness” of cancer cells, thus induce cancer invasion." (PMID 29137410, 2017). "CBX7 overexpression also resulted in reduced ZEB1 expression, a downstream target of the Wnt/β-catenin pathway and a classical EMT regulator in many types of cancer." (PMID 28388562, 2017). "Epithelial-mesenchymal transition (EMT) is regulated by various transcription factors, including Twist, Snail, Slug, ZEB1, and ZEB2, and are deregulated in many cancers." (PMID 28423495, 2017). "Previous studies have reported that miR-200c inhibits EMT processes in cancer cells by regulating the expression of EMT markers including E-cadherin, N-cadherin, TCF8/ZEB1, Snail, vimentin, and β-catenin." (PMID 28727734, 2017). "Expanding and differential roles of ZEB1 and ZEB2 have been identified in various types of cancers in recent years." (PMID 28618162, 2017). "High expression of the EMT-TFs ZEB1, SNAIL1 and SNAIL2 in cancer cells triggers the expression of stemness factors SOX2, BMI1 and OCT4." (PMID 28137272, 2017). "Metformin has also been shown to impede the generation of the cancer stem cell phenotype via transcriptional repression of key drivers of the EMT genetic program, such as ZEB1." (PMID 28147330, 2017). "ZEB1 is an important regulator of EMT and is a target of miR-150; Vimentin and E-cadherin, widely used indicators of stromal invasion by cancer cells, are strongly up- and down-regulated, respectively, during EMT." (PMID 27566559, 2016). "Reducing ZEB1 expression increases levels of ESRP1 and RAB25 in human cancer and vice versa, and in our study ZEB1 directly affected transcription of both genes." (PMID 26646320, 2016). "Compared with these two cancer cell lines, OSE and OVCA433 cells maintained high levels of MMP2 and ZEB1 in both Matrigel and collagen 3D cultures." (PMID 26684027, 2016). "Expression of ZEB1 has been shown recently to be a strong predictor of survival in PDAC and is a known TF inducing epithelial-mesenchymal transition (EMT) in cancer cells." (PMID 27520560, 2016). "The interaction between ZEB1 and E-cadherin has been exclusively studied in EMT of human cancer cells." (PMID 26924382, 2016). "The transcription factors ZEB1 and YAP function in different pathways yet both activate aggressive behaviour in cancer cells." (PMID 26876920, 2016).
cancer (continued). "We describe a direct interaction between ZEB1 and the Hippo pathway effector YAP, shifting ZEB1 from a repressor to a transcriptional activator and thereby linking two pathways with very similar cancer-promoting effects." (PMID 26876920, 2016). "Gregory and colleagues reported evidence that suggests an essential role for the miR-200 family members in regulation of ZEB1 and ZEB2 genes and in the induction of epithelial to mesenchymal transition (EMT) in several types of cancer." (PMID 27039384, 2016). "In this study, we focused on a transcription factor Zeb1, which is widely expressed in development and cancer and acts as an inducer of EMT and a regulator of cell migration in cancer cells." (PMID 27509493, 2016). "In consequence, ZEB1 switches its function to a transcriptional co-activator of a ‘common ZEB1/YAP target gene set', thereby linking two pathways with similar cancer promoting effects." (PMID 26876920, 2016). "Zinc finger E-box binding homeobox transcription factor 1 (ZEB1) is a transcription factor and a master regulator for EMT in several types of cancer." (PMID 27150059, 2016). "Both RAB25 and ESRP1 are strongly downregulated by the expression of ZEB1, the epithelial-mesenchymal transition (EMT) inducer, in a Tetracycline induced model of human cancer." (PMID 26646320, 2016). "Elevated expression of the EMT-inducing transcription factors Zeb1, Snail and Twist1 can promote EMT in multiple cancer types." (PMID 27121055, 2016). "ZEB1 is a driver of the EMT branch of epithelial plasticity, and it is a potential prognostic marker in a lot of cancers." (PMID 27036021, 2016). "Although, further studies are needed to figure out potential association with other EMT activating transcription factors such as Twist and Zeb1/2, to the best of our knowledge, this is the first evidence that CTMP modulates EMT in cancer." (PMID 27328758, 2016). "The transcriptional repressor zinc-finger E-box binding homeobox 1 and 2 (ZEB1 and ZEB2) are crucial inducers of EMT in various cancers and have been shown to promote invasion and metastasis of cancer cells." (PMID 27240340, 2016). "Promotion of invasion and metastasis via interaction with transcription factors ZEB1 and ZEB2, involved in EMT in other cancer types." (PMID 27148353, 2016). "An inverse relation between ZEB1 and the miR-200 family members has been reported to promote EMT and invasion in various cancers, including pancreatic cancer." (PMID 27240340, 2016). "Zeb1, a transcription factor containing 1117 amino acids, is an EMT marker in cancer metastasis of some tissues including kidney." (PMID 27509493, 2016). "We found that FLO-1 expressed significantly higher mRNA levels of the mesenchymal markers SNAI1, ZEB1 and ZEB2 compared to the other cancer cell lines." (PMID 27863424, 2016). "Since EMT plays an important part during cancer metastasis, we next investigated expressions of five transcriptional factors responsible for EMT by Western blot, including Zeb1, and 2, Snail, Slug, and Twist." (PMID 27110769, 2016). "Transcription factors, such as Snail, Slug, ZEB1, Twist, and ZEB2/SIP1, have been demonstrated to be capable of orchestrating EMT in cancer progression." (PMID 25645291, 2015). "Our results demonstrate that PPIX treatment inhibited the expression of vimentin, Zeb1/2, snail, slug, and twist, EMT markers upregulated in mesenchymal HCC cells, supportive of its anti-cancer potential against HCC with EMT phenotype." (PMID 25714015, 2015). "We propose that HIF-1α directly binds to the promoter of ZEB1 and serves as its critical positive regulator, thereby promoting EMT and cancer metastasis." (PMID 26057751, 2015).